MSH6 (mutS homolog 6)
Diseases named in the same sentence as MSH6 in open-access papers (continued):
Sharing a sentence is not in itself a finding about the gene and the disease.
endometrial cancer (continued). "Patients 4 and 5 with rectum cancers at age 71 demonstrated normal MMR efficiency, while Patient 6 with multiple LS spectrum cancers in first- and second-degree family members and the loss of MSH6 expression in her endometrial cancer tissue was shown to have MMR deficiency based on DiagMMR." (PMID 36875157, 2023). "In addition, we observed that one GIST patient with MSH6 mutation was diagnosed with endometrial cancer." (PMID 34805171, 2021). "Importantly, detection of MSH6 deficiency is in parts crucial, since females carrying a pathological MSH6 mutation are reported to be at especially high risk of endometrial cancer compared with other LS-related cancers." (PMID 33755781, 2021). "It became clear that endometrial cancer was part of LS and the revised Amsterdam II clinical criteria were agreed, including endometrial cancer as an affected phenotype and consistent with path_MSH6 being a cause of LS." (PMID 32190163, 2020). "In addition, a deleterious splice-site mutation in MSH6 was detected in ovarian and endometrial cancer patients, and ovarian cancer was diagnosed with mucinous carcinoma." (PMID 26436112, 2015). "Females in this patient cohort had a lifetime risk of endometrial cancer of 65% at 70 years of age, which is similar to previously reported risk figures for MSH6 mutation carriers but again much higher than risk figures produced from a much larger study population." (PMID 20487569, 2010). "In view of the disputable effect of endometrial carcinoma surveillance, in female MSH6 carriers aged 45 years or above prophylactic hysterectomy may be suggested in order to decrease the risk for developing endometrial carcinoma." (PMID 20028567, 2009). "Given the high mutation rate of MSH6 in endometrial cancer, we not only conducted analysis in unclassified tumor samples but also innovatively verified the results in the remaining MSH6 wild-type tumor samples after removing those with MSH6 mutants and obtained consistent results with them." (PMID 38390329, 2024). "And female MSH6 carriers may have the highest risk of endometrial cancer (EC)." (PMID 35311082, 2022). "In addition MSI analysis on endometrial cancer, the most frequent tumour in female MSH6 mutation carriers might decrease its sensitivity, as it is known that the instability in these tumours is generally less pronounced." (PMID 17117178, 2006).
endometrial cancer (continued). "There was a single case of a triple heterozygote (BRCA1/MLH1/MSH6; case 69) who developed endometrial cancer at age 41 years." (PMID 39843919, 2025). "In vitro experiments also confirmed that after knocking down MSH6 in endometrial cancer cells, their proliferation, migration and invasion abilities were weakened, while the expression levels of PD-L1 and PD-L2 were elevated." (PMID 38390329, 2024). "The nuclear model was further validated in MSH6 and PMS2 in endometrial cancer, where loss of expression was significantly associated with longer CSS for both manual and DL scores." (PMID 39040241, 2024). "Lemetre and Berg, respectively, used the TCGA database and their own endometrial cancer samples to analyze and found that MSH6 was an independent prognostic marker, and patients with low expression of MSH6 had better survival outcomes." (PMID 38390329, 2024). "Previous studies have indicated a notable discordance between IHC and molecular tests, especially in MSH6‐ and PMS2‐deficient endometrial carcinomas." (PMID 39132875, 2024). "Collectively, these studies suggest high MSH6 as a driver of aggressive disease, which should also be investigated in endometrial cancer." (PMID 36482191, 2023). "Prognostic value of MSH6 was further validated in hysterectomy tissue, at both protein and mRNA levels, and in the external TCGA endometrial cancer cohort." (PMID 36482191, 2023). "In conclusion, we here demonstrate that MSH6 can be used preoperatively as an independent prognostic marker in addition to its value as MMR-D classifier in endometrial cancer." (PMID 36482191, 2023). "The TCGA endometrial cancer (PanCancer Atlas) gene expression dataset was used to investigate the prognostic value of MSH6 in independent datasets." (PMID 36482191, 2023). "A nonsense nucleotide substitution in the MSH6 gene (NM_000179.3) was found in a patient affected by BC (onset at 34 years of age), who developed an endometrial cancer at follow-up." (PMID 36035419, 2022).
endometrial cancer (continued). "We review the frequency of this MMRD IHC pattern among 108 colorectal (CRCs) and 35 endometrial cancers in our files with loss of expression of at least one protein, and present two CRCs showing loss of PMS2 and MSH6 protein expression (1.9% of CRCs)." (PMID 32664968, 2020). "The result has been that most LS families identified historically have fulfilled these criteria and have dominantly inherited CRC/endometrial cancer with high penetrance, while relatively few path_MSH6 and very few path_PMS2 families have been identified." (PMID 32190163, 2020). "Path_MSH6 and path_PMS2 carriers have risks that are so low that when cured from CRC or endometrial cancers, any increased risk for other cancers is hardly measurable." (PMID 32190163, 2020). "In this study, we review the frequency of this IHC pattern among colorectal (CRCs) and endometrial cancers (ECs) in our files and present two CRCs showing loss of PMS2 and MSH6." (PMID 32664968, 2020).
endometrial cancer (continued). "Inherited or somatically acquired mutations of MSH6, although relatively uncommon in endometrial cancers in general, are often seen in MSI endometrial cancer." (PMID 23743825, 2013). "Endometrial cancer was seen in 59% of the MSH6 families as the second most common malignancy observed." (PMID 20487569, 2010). "The superior performance of the pentaplex assay over the NCI panel is particularly evident for tumours with defective MSH6 and for endometrial cancer samples." (PMID 21081928, 2010). "It underlines that female MSH6 mutation carriers have a distinct clinical phenotype with a lower CRC risk and a higher risk for developing endometrial carcinoma." (PMID 20028567, 2009). "MSH6 mutation families probably have a milder clinical phenotype with a later onset of both CRC and EC and clustering of endometrial carcinoma." (PMID 20028567, 2009). "Female MSH6 mutation carriers have a lower CRC risk and a higher risk for developing endometrial carcinoma." (PMID 20028567, 2009). "MSH6, an MMR protein, is less studied in LS, and the exact mechanism of inconsistent MSI and MMR results among endometrial cancer (EC) patients who are carriers of MSH6 mutations remains unclear." (PMID 40469174, 2025). "Furthermore, to our knowledge, we are the only study that analyzed the relationship between MSH6, immune infiltration and ICIs treatment responsiveness in endometrial cancer." (PMID 38390329, 2024). "It is well known that isolated loss of MSH6 in endometrial cancer is relatively frequent and MSI PCR is not sensitive enough to detect the resulting microsatellite alterations." (PMID 38350968, 2024). "We demonstrate that in addition to determine MMR status, MMR protein expression levels, particularly MSH6, may add prognostic information in endometrial cancer." (PMID 36482191, 2023). "However, the prevalence of mutations in MSH6 and PMS2 in endometrial cancer patients with LS has been reported to be 52–72% in recent studies, as determined using multigene panel tests." (PMID 35884469, 2022). "Reduced or no MSI together with isolated MSH6 loss has been rarely observed in colorectal and endometrial carcinomas and has been attributed to partial impairment of MMR function." (PMID 35099128, 2022). "Mutations in the MSH6 gene are frequently associated with HNPCC, CRC and endometrial carcinoma." (PMID 32756484, 2020).
endometrial cancer (continued). "The pathogenic variants in BC-related genes (2 in ATM and 1 in BRCA2) were found in 3 women with BC or ovarian cancer, while the MSH6 and the heterozygous MUTYH p.Gly393Asp pathogenic variant was found in a woman with endometrial cancer at 57 years and BC diagnosis at 56 years, respectively." (PMID 29371908, 2018). "MSH6 mutations are rarer than mutations in the other two genes, being found in 10–20% of HNPCC cases, who often have an atypical presentation and increased predisposition to endometrial cancer." (PMID 24357391, 2014). "The relatively high frequency of MSH6 mutations and older age at onset appears to be characteristic of mutation carriers from unselected endometrial cancer populations not restricted by age at diagnosis (or with cut-off at a late age)." (PMID 24056992, 2013). "HNPCC patients with endometrial cancers have an inherited germline mutation in MLH-1, MSH-2, MSH-6, or PMS-2, but endometrial cancer only develops after the instauration of a deletion or mutation in the contralateral MLH-1, MSH-2, MSH-6, or PMS-2 allele." (PMID 20396392, 2010). "Cancer incidence in the MSH6 mutation positive families includes, in order of frequency (in how many families the cancer was observed): CRC in 23 families (79%); cancer of the endometrium in 17 families (59%); breast or prostate cancer in 7 families (24%); and ovarian cancer in 5 families (17%)." (PMID 20487569, 2010). "Segregation analysis in the family showed that her brother who had a glioma, and the mother who had two sisters with anamnestic endometrial cancer did not carry the MSH6 variant, making the pathogenecity of this variant less likely." (PMID 17117178, 2006). "In the MSH6 families endometrial cancers occur as frequently as CRCs." (PMID 17117178, 2006). "The cell proliferation and clonal formation assay indicated that the proliferation ability of endometrial cancer cells after MSH6 knockdown was significantly weaker than that of the control group, while it was significantly stronger than that of the control group after overexpression of MSH6." (PMID 38390329, 2024). "Collectively, if MSH6 is thoroughly evaluated, this marker may aid in prognostication of endometrial cancer patients preoperatively, thus refining patient stratification for invasive surgery and adjuvant therapy, and in addition function as an MMR-D classifier." (PMID 36482191, 2023). "Patients with germline mutations in MSH6 are more likely to develop endometrial cancer and may not test positive for MSI by PCR." (PMID 28259170, 2017). "The potential targets for targeted treatment of endometrial cancer (KRAS, PIK3CA, MLH1, MSH6, POLE, PTEN) showed more significant changes in the supernatant of vaginal lavage fluid." (PMID 41602422, 2026).